FOXC2 (forkhead box C2)
Diseases named in the same sentence as FOXC2 in open-access papers (continued):
Sharing a sentence is not in itself a finding about the gene and the disease.
lymphedema (continued). "The FOXC2 mutation was also found in family members who had no SEDAC but had lymphedema or distichiasis; the penetrance of SEDAC was 70%; distichiasis, 70%; and lymphedema, 20%." (PMID 24278289, 2013). "FOXC2 pathogenetic variant has been identified in cases with LDS to impair transcriptional activity and cell proliferation through VEGF-C/VEGFR3 signaling pathway commonly correlated with primary lymphedema, lymphatic valve formation and other lymphatic malformations." (PMID 36329475, 2022). "Therefore, we have hypothesized that the deletion might disrupt the transcriptional network of FOXC2, possibly leading to lymphedema in the carriers of chr16q24.2 deletion." (PMID 35227307, 2022). "Interestingly, although FOXC2 gene mutations were closely associated with venous valve failure and were seen in carriers, these individuals did not have lymphedema." (PMID 24228622, 2013). "Thus, the increased nuclear activity of β-catenin in LECs specifically induced the formation of lymphatic valves in the Foxc2 heterozygous mice and rescued the valve loss in this mouse model of lymphedema-distichiasis without altering the expression of junction proteins and SMC coverage." (PMID 36742198, 2022). "Mutations associated with the VEGF-C/VEGR3 signaling pathway, including changes in FOXC2, as well as key transcription factors involved in LEC specification, such as Sox-18 and GATA2, contribute to the development of primary lymphedema." (PMID 32510325, 2020). "Several genes specifically have been associated with named lymphatic diseases, such as SOX18 in hypotrichosis-lymphedema-telangiectasia, FOXC2 in lymphedema-distichiasis, and VEGFR3 in Nonne–Milroy disease." (PMID 35743063, 2022). "Downregulation of FOXC2 was noted in both the VLNT and lymphedema groups." (PMID 36176614, 2022). "Unlike mouse Foxc1 and Foxc2, foxc1a alone is required in multiple tissues, with single foxc1a mutant zebrafish exhibiting heart defects, circulatory defects, and lymphedema." (PMID 34716915, 2021). "In addition, mutations in VEGFR3 and FOXC2 are linked to rare lymphatic disorders called Nonne–Milroy lymphedema (OMIM 153100) and lymphedema–distichiasis syndrome (LDS, OMIM 153400), respectively." (PMID 31908356, 2020). "It is however not known if MCLMR patients have lymphatic hyperplasia as observed in FOXC2-mutated patients (lymph and venous reflux and failure or absence of lymphatic and venous valves) or hypoplasia as seen in VEGFR3-mutation caused Nonne-Milroy lymphedema." (PMID 25934493, 2015). "Furthermore, no FOXC2 mutations were found in 6 subjects who belonged to the family and did not have any symptoms of SEDAC, distichiasis, or lymphedema." (PMID 24278289, 2013).
lung carcinoma (19 papers, 2016 to 2025). "Of significance, a naturally occurring FOXC2-H122N mutation is reported in lung cancers." (PMID 40464693, 2025). "In a clinical trial carried out on 96 lung cancer patients, resveratrol suppressed tumor growth by downregulating Forkhead box C2 (FOXC2) and upregulating miR-520h-mediated PP2A/C expression, thereby causing apoptosis in lung cancer cells." (PMID 37568796, 2023). "FOXC2 overexpression has been reported in a range of tumor kinds, including lung cancer, colorectal cancer, gastric cancer, ovarian cancer and glioma." (PMID 36425886, 2022). "A study has found that RES inhibited miRNA-520h, activated protein phosphatase 2 A/C (PP2A/C), then through the AKT-NF-κB signaling axis, finally down-regulated FOXC2 to inhibit distant metastasis of lung cancer cells." (PMID 33937049, 2021). "Several EMT-TFs such as Slug, Twist, ZEB1, and FOXC2 had higher immunoreactivity in brain metastasis than lung cancer." (PMID 33291558, 2020). "This seems to support the role of FoxC2 as a strong repressor of E-cadherin in lung cancer." (PMID 26758745, 2016). "Similarly, lung cancer patients with high expression of FOXC2 also experience a poor prognosis." (PMID 33937049, 2021). "Similar observations have been reported in breast and lung cancer cell lines where induction of FOXC2 expression by inorganic phosphate facilitated HUVEC tube formation and migration in the presence of conditioned media from FOXC2-expressing cancer cells." (PMID 36230774, 2022). "Since the FOXC2 is a key regulator that activates epithelial-mesenchymal transition (EMT) and metastasis, suppression of FOXC2 by resveratrol-mediated regulation of the miR-520h-PP2A/C axis induces mesenchymal-epithelial transition (MET) and exerts anticancer effects in lung cancer cells." (PMID 31126043, 2019). "However, despite all these biochemical and functional findings, the prognostic role of FoxC2 in cancers has not been extensively studied, especially in the context of lung cancer." (PMID 26758745, 2016).
gastric cancer (16 papers, 2014 to 2023). A primary or metastatic malignant neoplasm involving the stomach. "Recent studies have reported that FOXC2 is dysregulated in malignancies, including breast cancer, gastric cancer, esophageal carcinoma." (PMID 36425886, 2022). "Our data showed that the expression of FOXM1 was significantly reduced in PAX8-overexpressing gastric cancer cells, but FOXC2, FOXF1, and FOXL1 remained unchanged." (PMID 30021604, 2018). "Endogenous SUMO2/3 modifications on endogenous FOXC2 were further analyzed in the tissues obtained from the orthotopic gastric cancers in the mouse model." (PMID 25216525, 2014). "First, both exogenous and endogenous SUMO2/3 conjugations on FOXC2 are detectable in gastric cancer cells." (PMID 25216525, 2014). "In conclusion, SENP3, which is increased in gastric cancer cells, potentiates the transcriptional activity of FOXC2 through de-SUMOylation, in favor of the induction of specific mesenchymal gene expression in gastric cancer metastasis." (PMID 25216525, 2014). "SNEP3 activates the transcriptional activity of forkhead box protein C2 (FOXC2) and increases the expression of N-cadherin through the deSUMOylation of FOXC2, which activates the transformation of epithelial mesenchyme as well as enhances the invasion and metastasis of gastric cancer cells." (PMID 37777749, 2023). "Besides, Shen found that YTHDF2 recognized and mediated the m6A modification of FOXC2 and restrained gastric cancer cell growth via degrading FOXC2, but which “writer” added the m6A modification of FOXC2 mRNA in this study was still unclear." (PMID 36870954, 2023). "YTHDF2 reduced cell growth by targeting FOXC2 pathway in gastric cancer." (PMID 36003776, 2022). "Overexpression of YTHDF2 significantly inhibited the proliferation, invasion and migration of gastric cancer cells by negatively regulating forkhead box C2 (FOXC2), which acts as an oncogene in various cancers such as nasopharyngeal cancer, colorectal cancer and triple negative breast cancer." (PMID 33928028, 2021). "SENP3 promotes EMT in gastric cancer cells by regulating the EMT inducer FOXC2." (PMID 33192553, 2020). "For example, SENP3 deSUMOylates the HIF1α coactivator P300 to increase angiogenesis under hypoxia, deSUMOylates promyelocytic leukemia in response to mild oxidative stress, and de-SUMOylating FOXC2 to facilitate epithelial-mesenchymal transition in gastric cancer cells." (PMID 30640896, 2019). "We demonstrate that FOXC2 and FOXQ1 areboth associated with gastric cancer progression.Therefore, both may potentially be used as targetsfor prognosis of patients." (PMID 28580309, 2017). "Importantly, de-conjugation of SUMO2/3 from FOXC2 by SENP3 exists endogenously in gastric cancer cells." (PMID 25216525, 2014). "The SENP3 level is increased in gastric cancer cells, and SENP3 deSUMOylates FOXC2, potentiates its transcriptional activity, induces the epithelial cell to interstitial cell changes, and promotes tumor invasion and metastasis." (PMID 33192553, 2020). "The present study uncovers a novel role of SENP3 in promoting the EMT process in gastric cancer via regulating an EMT-inducing transcription factor, forkhead box C2 (FOXC2)." (PMID 25216525, 2014). "However, high level expression of FOXC2 and PABPC1 in gastric cancer as well as in the activation of epithelial mesenchymal transition (EMT) and metastasis by overexpression of FOXC2 in cancer cells are potentially consistent with their role in suppressing the p16INK4a-dependent senescence." (PMID 34634809, 2022).
lymphedema-distichiasis syndrome (16 papers, 2012 to 2025). "Pathogenic FOXC2 gene variants cause lymphedema-distichiasis syndrome and have been associated with spinal extradural arachnoid cysts in several publications." (PMID 38052889, 2024). "FOXC2 is essential for lymphatic valve development and maintenance, and heterozygosity for Foxc2 causes lymphedema distichiasis." (PMID 37655664, 2023). "For example, a frameshift mutation of FOXC2 is associated with lymphedema-distichiasis and diabetes while the FOXC2 C-512T polymorphism is associated with obesity, dyslipidemia, and diabetes." (PMID 36230774, 2022). "Dominant mutations in the FOXC2 gene (MIM *602402) are linked to lymphedema-distichiasis (LD) syndrome (MIM #153400) and cause pleiotropic effects in different types of tissue." (PMID 32698337, 2020). "Mutations in FOXC2 have been associated with lymphedema distichiasis (LD), an autosomal dominant disorder that primarily affects the limbs." (PMID 32698337, 2020). "Mutations in Foxc2 are responsible for the hereditary lymphedema-distichiasis syndrome with CP observed in some patients." (PMID 23421592, 2013). "FOXC2 is the transcription factor associated with lymphedema-distichiasis (LD, OMIM #153400) a monogenic disorder that is characterized by late onset LE, a double row of eyelashes, and varicose veins." (PMID 23613720, 2013). "Furthermore, we observed that FOXC2 which is linked with lymphedema distichiasis syndrome (LDS) was located 550 kb downstream to the chr16q24.2 deletion." (PMID 35227307, 2022). "FOXC2 mutations cause Lymphedema-distichiasis syndrome (LD)." (PMID 33925370, 2021). "Four genes were found to be involved in four cases each: the RAPSN gene related to fetal akinesia syndrome II, the SLC26A3 gene related to congenital chloride diarrhea, the L1CAM gene related to hydrocephalus with X-linked inherence, and the FOXC2 gene related to lymphedema-distichiasis syndrome." (PMID 34682862, 2021). "Interestingly, FOXC2 has been identified as the key gene responsible for Lymphedema-Distichiasis Syndrome (LDS, MIM 153400), a condition characterized by limb lymphedema and a double row of eyelashes." (PMID 40869921, 2025). "In the group of fetuses with the isolated increased nuchal translucency a small interstitial 16q24.1 deletion was identified, involving FOXF1 gene (Alveolar capillary dysplasia with misalignment of pulmonary veins, ACDMPV, OMIM#265380) and FOXC2 gene (Lymphedema-distichiasis syndrome, OMIM#153400)." (PMID 27846804, 2016).
ovarian carcinoma (16 papers, 2016 to 2025). A malignant neoplasm originating from the surface ovarian epithelium. "Expression of nuclear FOXC2 has been associated with aggressiveness and advanced stage in most cancers, including ovarian cancer." (PMID 36230774, 2022). "The present study is aimed at exploring the correlation between the polymorphism of FOXC2 and epithelial ovarian cancer susceptibility in Chinese Han population." (PMID 32222147, 2020). "In the current case-control study with 150 epithelial ovarian cancer cases and 298 healthy controls from Chinese populations, we explored the potential association between FOXC2 gene polymorphisms and epithelial ovarian cancer susceptibility." (PMID 32222147, 2020). "This study focused on the relevance between the polymorphism of FOXC2 and epithelial ovarian cancer susceptibility." (PMID 32222147, 2020). "A case-control design was used to verify the association between FOXC2 polymorphisms and epithelial ovarian cancer." (PMID 32222147, 2020). "So far, the current study is the first to evaluate the association between FOXC2 polymorphisms and epithelial ovarian cancer susceptibility." (PMID 32222147, 2020). "In addition, we showed that FOXC2 expression is associated with vasculogenic mimicry in mouse and human ovarian cancers." (PMID 36230774, 2022). "Additionally, we found evidence that FOXC2 expression is associated with vasculogenic mimicry in ovarian cancer samples and that FOXC2 overexpression promotes vasculogenic mimicry in cell culture." (PMID 36230774, 2022). "To detect if FOXC2 expression is associated with the formation of VM structures in mouse tumors that were generated by intraperitoneal and subcutaneous injection of mouse ovarian cancer cell lines transduced with GFP or FOXC2, we double-stained tumor sections with CD31 antibody and PAS." (PMID 36230774, 2022). "The results of the current study verified that FOXC2 gene polymorphisms were associated with increased epithelial ovarian cancer risk and suggested that FOXC2 gene polymorphisms might be a potential biomarker for epithelial ovarian cancer susceptibility." (PMID 32222147, 2020). "In ovarian cancer, stanniocalcin 1 enhances metastatic capacity, lipid metabolism, and cisplatin resistance through the FOXC2/ITGB6 signaling pathway." (PMID 40746552, 2025). "Analysis of publicly available gene expression data from several other solid tumor types showed elevated levels of FOXC2-target genes in aggressive subtypes of colorectal cancer, glioblastoma and ovarian carcinoma." (PMID 37499655, 2023). "Together, these data show that the FOXC2-expressing mouse ovarian cancer cell lines exhibit phenotypic characteristics similar to those described in human ovarian, breast, and other cancer cell lines." (PMID 36230774, 2022). "The more rapid formation of subcutaneous tumors in the presence of FOXC2 was confirmed in four additional primary mouse ovarian cancer cell lines that contained different combinations of genetic alterations." (PMID 36230774, 2022). "Although our study was focused on ovarian cancer, FOXC2 has been shown to induce EMT and CSC differentiation in other aggressive malignancies, and EMT-facilitated CSC differentiation has been linked to VM in several cancer types." (PMID 36230774, 2022). "To gain further insight into the potential role of FOXC2 in ovarian cancer progression, we analyzed the effects of FOXC2 overexpression on tumor formation in xenografts in nude mice." (PMID 36230774, 2022). "We did not observe upregulation of prototypical endothelial cell markers (CD31, CD34, VE-cadherin, Icam1, and Vcam1) upon ectopic expression of FOXC2 in mouse ovarian cancer cells." (PMID 36230774, 2022). "Downregulation of these cell markers suggested that FOXC2 overexpression induced trans-differentiation of the mouse ovarian cancer cell lines." (PMID 36230774, 2022).
ovarian carcinoma (continued). "We confirmed that FOXC2 can promote VM in human ovarian cancer cell lines in vitro and showed that vascular channels indicative of VM are present in FOXC2-expressing mouse and human ovarian cancers." (PMID 36230774, 2022). "Our study contributes to the understanding of VM in ovarian cancer by identifying FOXC2 as another transcription factor involved in VM in ovarian cancer." (PMID 36230774, 2022). "Both FOXC2 expression and the presence of VM have been shown to correlate with poor survival in previous ovarian cancer studies." (PMID 36230774, 2022). "Angpt2, which we found to be upregulated in FOXC2-expressing mouse ovarian cancer cell lines, has been previously identified as a mediator of tumor angiogenesis." (PMID 36230774, 2022). "FOXC2 overexpression increased the ability of human ovarian cancer cells to form vascular-like structures in vitro, while inhibition of FOXC2 had the opposite effect." (PMID 36230774, 2022). "Here, we show that the EMT and CSC marker, FOXC2, is involved in VM in ovarian cancer." (PMID 36230774, 2022). "Increased mRNA expression of the mural cell markers Cspg4 (NG2), Anpep (CD13), and Pdgfrb in FOXC2-expressing ovarian cancer cell lines suggested possible trans-differentiation of epithelial cancer cells into mural cells, a phenomenon that has been associated with VM." (PMID 36230774, 2022). "FOXC2 could mediate platinum resistance in ovarian cancer cells through activation of the AKT and MAPK pathways." (PMID 31213009, 2019). "Moreover, FOXC2 was required for maintaining the mesenchymal phenotype after TGF-β1-induced EMT in human ovarian cancer cells." (PMID 27882939, 2016). "Additionally, mural cell markers, such as chondroitin sulfate proteoglycan 4 (Cspg4, also known as NG2), alanyl membrane aminopeptidase (Anpep, also known as CD13), and platelet-derived growth factor receptor beta (Pdgfrb), were upregulated in FOXC2-expressing ovarian cancer cells." (PMID 36230774, 2022). "Using in vitro and in vivo assays in mouse ovarian cancer cell lines, we confirmed the previously reported mechanisms by which FOXC2 could promote cancer growth, metastasis, and drug resistance, including epithelial-mesenchymal transition, stem cell-like differentiation, and resistance to anoikis." (PMID 36230774, 2022). "Moreover, FOXC2 was high expression in invasive ovarian cancer tissues and cell lines." (PMID 29050292, 2017). "For example, STC1 promotes ovarian cancer metastasis, lipid metabolism, and DDP chemotherapy resistance through the FOXC2/ITGB6 signalling pathway." (PMID 38556542, 2024). "Forkhead box protein C2 (FOXC2) has similar effects by activating Akt and/or ERK in platinum-resistant ovarian cancer cell lines." (PMID 32767962, 2021). "Still FOXC2 was certificated to promote EMT, migration and invasion in cisplatin-resistant ovarian cancer cells." (PMID 32222147, 2020). "This is exemplified by FOXC2, a member of the forkhead box (FOX) transcription family, which induced resistance to platinum-based chemotherapy in ovarian cancer cells by activating the AKT and MAPK pathways." (PMID 31213009, 2019). "In the ovarian cancer tissues, further significant positive correlations were observed between DAB2 and CSC markers (CD34, ALDH1A1, CD117 (Kit)) and mesenchymal markers (MMP9, SNAI1 and MMP3) and negative correlations with mesenchymal markers (CDH2, FOXC2 and SOX10)." (PMID 37815603, 2023).